RORA (RAR related orphan receptor A)
Diseases named in the same sentence as RORA in open-access papers (continued):
Sharing a sentence is not in itself a finding about the gene and the disease.
breast carcinoma (continued). "Moreover, RORα expression suppresses proliferation, promotes apoptosis, and inhibits invasion in breast cancer cells." (PMID 41425709, 2025). "It is important to determine whether this pathway contributes to the downregulation of RORα during breast cancer development and progression in the future." (PMID 38791992, 2024). "Reduced levels of RORα and SEMA3F have been found to be linked to poor clinical outcomes in human breast cancer cells; however, RORα activation suppresses aggressive phenotypes, tumor invasion, and growth of breast cancer cells in vivo." (PMID 39518891, 2024). "Moreover, RORA has been shown to decrease inflammation in breast cancer cells by inhibiting reactive oxygen species-mediated cytokine expression." (PMID 39010137, 2024). "We show that RORα expression significantly inhibits Snail transcription in breast cancer cells." (PMID 35605663, 2022). "RORA is also a potential target in breast cancer that negatively modulates angiogenesis." (PMID 35414788, 2022). "To determine whether RORα expression suppresses breast cancer metastasis, we injected control and RORα-expressing MDA-MB-231-luc cells (luciferase-labeled) in SCID mice via the tail vein." (PMID 34639006, 2021). "In contrast, the overexpression of RORα in breast cancer cells elevated OCR." (PMID 34639006, 2021). "To determine whether the RORα/complex I axis inhibits electron leakage in mitochondria, we measured superoxide anion levels with mitoSOX red in control and RORα-expressing breast cancer cells." (PMID 34639006, 2021). "To determine how RORα suppresses breast cancer progression, we performed gene expression profiling analysis in MDA-MB-231 and MDA-MB-157 cells with Affymetrix Exon Array, and identified many genes being differentially expressed in control and RORα-expressing cells." (PMID 34639006, 2021). "In addition, CRY2 and RORA genes were denoted for the effect on breast cancer though the interaction with other genes or with an environmental factor (NSW)." (PMID 31358835, 2019). "Additionally, RORα binds to β-catenin that suppresses Wnt/β-catenin gene transcription, known to be an important pathway in breast cancer cell adhesion and cell growth." (PMID 29497051, 2018). "Baek and colleagues have demonstrated that RORα is downregulated in breast cancer." (PMID 27602774, 2016). "In addition, crosstalk among those pathways has been observed in vitro and in vivo; therefore, an integrated view of RORα downstream signaling is crucial for our understanding of roles of this protein in breast cancer progression." (PMID 23443091, 2012). "Expression of RORα is downregulated in breast cancer tissues and cell lines." (PMID 23443091, 2012). "Moreover, silencing SEMA3F expression in RORα-expressing breast cancer cells rescues the invasive phenotypes in 3D culture, suggesting that tumor suppressor function of RORα is at least partially conferred by SEMA3F." (PMID 23443091, 2012). "Expression of RORα suppresses malignant phenotypes in breast cancer cells, in vitro and in vivo." (PMID 23443091, 2012). "Based on these observations and given the recent progress characterizing RORα agonists, further investigations of tumor suppressor activities by RORα in breast cancers may lead to the discovery of novel therapeutic targets for this mortal disease." (PMID 23443091, 2012). "The hierarchical regulatory network analysis with DREM and Cytoscape revealed that RORA could be a potential ERα partner, which is consistent to other reports showing that RORA interacts with ERα and enhances ER transcriptional activity in breast cancer." (PMID 21167036, 2010).
breast carcinoma (continued). "Studies suggest that in estrogen receptor-positive (ER-positive) breast cancer, RORA may enhance cancer cell proliferation through the upregulation of aromatase expression, potentially contributing to tumorigenesis.In contrast, RORA displays tumor-suppressive activity in other cancer types." (PMID 40638694, 2025). "Similarly to the case of an inverse correlation between oncogenic EZH2 and tumor-suppressive RORα in breast cancer, we speculate that the potential oncogenic function of G9a might be augmented by the degradation of FOXO1, which is a known tumor suppressor." (PMID 36639369, 2023). "Interestingly, the levels of EZH2 and RORα were inversely correlated in breast cancer, implying that EZH2 might play an oncogenic role by inhibiting RORα-mediated tumor suppression." (PMID 36076977, 2022). "Moreover, recent studies have suggested that RORA may also play a role in the progression and prognosis of colon cancer and breast cancer." (PMID 34285836, 2021). "Notably, the reduced RORα expression in primary breast cancer correlated with poor prognosis." (PMID 34639006, 2021). "In addition, tumor cell growth in soft agar could be suppressed in the breast cancer cell line MCF7 by ectopically expressing RORα, inhibiting EZH2 activity, or silencing VprBP." (PMID 24028781, 2013). "We and others recently showed that the orphan nuclear receptor RORα is downregulated in cancer tissues and cell lines and that expression of RORα results in tumor suppressive activities, suggesting that RORα is a potential drug target for breast cancer treatment." (PMID 23443091, 2012). "However, it remains to be determined whether RORα modulates circadian rhythms in breast cancer cells and how disruption of circadian rhythms promote breast cancer progression." (PMID 23443091, 2012). "Thus, it is worthwhile to explore whether the RORα suppresses breast cancer progression through inhibition of the NF-κB signaling pathway." (PMID 23443091, 2012). "Thus, it is important to explore whether the RORα plays a key role in melatonin-mediated inhibition of cell invasion and proliferation of breast cancer cells." (PMID 23443091, 2012). "The findings that RORα suppresses EMT and Snail expression provide additional insights in the function of RORα in breast cancer metastasis." (PMID 35605663, 2022). "Silencing RORα in S1 cells and MCF-10A cells increased the IL-6 protein levels in the conditioned medium, while overexpression of RORα decreased the level in breast cancer cells." (PMID 34639006, 2021). "We also found that the expression of RORα negatively correlated with NDUFS6 and NDUFA11 mRNA levels in human breast cancer tissue (TCGA breast cancer dataset)." (PMID 34639006, 2021). "Several actions for RORα have also been found in melanoma and breast cancer, and the presence of RORα mRNA has been reported both in TNBC and ER-positive human breast cancer cells." (PMID 31311992, 2019). "Although GAIT activity has not been demonstrated in other cell types, including breast cancer cells, several genes predicted to be regulated by GAIT, such as RORA, NRIP1, and DZIP3 have been shown to mediate ERα-dependent proliferation of breast cancer cells." (PMID 27612429, 2016). "Consistent with data suggesting EZH2 regulates RORα levels, the authors showed that breast cancer cells and tumors which overexpress EZH2 have lower RORα levels compared to normal controls." (PMID 24028781, 2013). "Therefore, RORα may suppress breast cancer progression by inhibiting Wnt/β-catenin target genes." (PMID 23443091, 2012).
breast carcinoma (continued). "Treatment with the RORα antagonist (SR1001) enhanced tumorsphere formation efficiency in MDA-MB 231 and HMT-3522 T4-2 cells, whereas the RORα agonist (SR1078) depressed tumorsphere formation in breast cancer cells." (PMID 35605663, 2022). "The knockdown of RORα significantly elevated ROS levels in non-malignant mammary epithelial cells, while introducing RORα in breast cancer cells reduced ROS production." (PMID 34639006, 2021). "From two pairs of matched breast cancer samples, we found that some of the detected CNVs contained some genes that were related to breast cancer, such as PDZK1, XRCC4, Fbxl17, ITGBL1, RORA, BAGE, AMOTL1, RAP80, PIWIL4, CSE1L, and USP18." (PMID 34262604, 2021). "In addition, the upregulation of complex I subunits in RORα-silenced mammary epithelial cells was accompanied by reduced OCR, while silencing NDUFS6 and NDUFA11 increased OCR in breast cancer cells." (PMID 34639006, 2021). "RORα was suggested to function as a tumor suppressor—activation of RORα attenuates migratory and invasive features of androgen-independent prostate cancer, reduces WNT/β-catenin signaling in colon cancer, and suppresses proliferation of breast cancer cells." (PMID 33327550, 2020). "In addition, putative gene interactions between NPAS2, CUL1 and RORA, CLOCK and CUL1 is observed to have correlation in the development of breast cancer." (PMID 31358835, 2019). "Melatonin also modulates RORα transcription after the indoleamine interacts with the MT1 membrane receptor; this may also relate to breast cancer." (PMID 28420185, 2017). "While retaining all beneficial features of RORα in breast cancer cells, our results propose that RORα2 and LSD1 may play crucial roles in tumorigenesis via elevating CTNND1 expression in human breast cancer." (PMID 28931919, 2017). "Activity of RORα can be categorized into the canonical and non-canonical nuclear receptor pathways, which in turn regulate various breast cancer cellular function, including cell proliferation, apoptosis and invasion." (PMID 23443091, 2012). "Moreover, RORA is known to function as an important negative modulator of angiogenesis in breast cancer to suppress its progression." (PMID 35414788, 2022). "Reduced RORα expression is detected in non-polarized breast cancer cells and terminal end buds." (PMID 34639006, 2021). "However, the mechanisms of RORα downregulation in breast cancer cells are not fully understood." (PMID 38791992, 2024). "Thus RORα may have different activity in ER-positive and -negative breast cancer cells, and the mechanism whereby RORα differentially regulates cellular response in ER-positive and -negative cells remains to be elucidated." (PMID 23443091, 2012). "The negative correlation between RORα expression and mRNA levels of NDUFS6 and NDUFA11 suggests that these two genes are the major targets of RORα mediating its function in ROS regulation during breast cancer progression." (PMID 34639006, 2021).
autism (42 papers, 2011 to 2025). Persistent deficits in social interaction and communication and interaction as well as a markedly restricted repertoire of activity and interest as well as repetitive patterns of behavior. "Transcription factor binding sites in the promoter regions of differentially expressed Alu elements are conserved and associated with autism candidate genes, including RORA." (PMID 37108679, 2023). "We evaluated the potential effect of intestine-specific RORA deficiency on maternal diabetes-mediated gene expression and autism-like behaviors." (PMID 35164690, 2022). "Dual molecular effects of retinoic acid receptor-related orphan receptor α (RORα) dominant mutations cause two variants of syndromic intellectual disability, resulting in either autism or cerebellar ataxia." (PMID 32392803, 2020). "All of these associated functions implicate RORA as a potential autism susceptibility gene with a significant role in autism pathogenesis." (PMID 28042538, 2017). "The staggerer mouse has a mutation of the retinoic acid receptor-related orphan receptor alpha (RORα) gene which has been associated with autism." (PMID 23717269, 2013). "This indicates that RORA may also play a role in OXT expression that adds to the significant effect of ERβ, which is consistent with previous findings that RORA plays a critical role in embryo development and is associated with autism development." (PMID 35370982, 2022). "RORα has also been linked to neurologic disorders, including autism, in humans." (PMID 36243007, 2022). "Furthermore, IEC-specific RORA deficiency mimicked or worsened maternal diabetes-mediated GI symptoms, while surprisingly, it showed little effect on maternal diabetes-mediated autism-like behaviors." (PMID 35164690, 2022). "Dominant-acting RORα mutations are associated with autism and cerebellar ataxia in humans." (PMID 35309302, 2022). "Furthermore, a direct association was performed between autism and RORA as a novel candidate gene in autism, directly implying a role of Cytochrome P450 17A1 (CYP17A1; also P450c17 and P450sccII)." (PMID 35743898, 2022). "RORA has been shown to be linked to other genes previously implicated in AD and also has been implicated in a large number of neuropsychiatric disorders, such as post-traumatic stress disorder and autism." (PMID 31283791, 2019). "Thus, the neuronal activities and high level neurological functions associated with these validated transcriptional targets of RORA suggest a mechanism for induction of autism brain pathology driven by sex hormones under conditions of RORA deficiency." (PMID 26056561, 2015). "These strong genetic associations of putative RORA targets with ASD risk further suggest that RORA deficiency may have a large impact on neuronal functions disrupted in autism." (PMID 26056561, 2015). "In addition, 1 feedback mechanism regulating sex hormonal activity is the RORA gene (and associated molecular mechanisms), which also directly regulates autism risk genes." (PMID 25524786, 2015). "Augmented levels of certain steroids may in turn alter the expression of genes implicated in autism pathogenesis such as Reelin and RORA." (PMID 24043498, 2014). "The proposition that epigenetic regulation of the retinoic acid-related orphan receptor alpha (RORA) might cause autism is relatively new." (PMID 24151554, 2013). "Finally, we demonstrate the correlated decrease of both RORA and aromatase protein levels in autistic brain, further strengthening support for RORA as a critical candidate gene for autism susceptibility." (PMID 21359227, 2011). "That is, estrogens may not only protect females against autism by increasing the level of RORA expression, but also by inducing shared target genes of RORA through ER, thus compensating in part for RORA deficiency." (PMID 21359227, 2011).
autism (continued). "We suggest that RORA may be a molecular link between the sex hormones and neurodevelopment as well as a mediator of at least some of the pathobiological processes associated with autism." (PMID 26056561, 2015). "In addition, the ASD associated gene RORA, an essential gene for normal development of cerebellar Purkinje neurons can harbour loss-of-function variants causative of LD with autism in humans that might represent a point of both genetic and environmental vulnerability for ASD." (PMID 40723391, 2025). "Sex differences in the expression of RORα and its target genes in the brain have been investigated as a potential contributor to the sex bias in autism." (PMID 41245836, 2025). "Male and female hormones differentially regulate the expression of a novel autism candidate gene, retinoic acid-related orphan receptor-alpha (RORA), in a neuronal cell line, SH-SY5Y." (PMID 41245836, 2025). "Genetic and functional analyses have found that RORA has regulatory effects on over 2500 genes, and more than 400 of these genes are considered risky for autism." (PMID 37525665, 2023). "We conclude that RORA suppression contributes to maternal diabetes-mediated GI symptoms in autism-like mouse offspring, this study provides a potential therapeutical target for maternal diabetes-mediated GI symptoms in offspring through RORA activation." (PMID 35164690, 2022). "In this study, we found that maternal diabetes-mediated autism-like mouse offspring have suppressed expression of RORA and its target gene in addition to oxidative stress and inflammation in brain tissues, PBMC and IEC, as well GI symptoms." (PMID 35164690, 2022). "In this study, we aim to investigate the potential role of RORA on GI symptoms in maternal diabetes-mediated autism-like mouse models." (PMID 35164690, 2022). "Our results showed that maternal diabetes-mediated autism-like offspring had significant GI symptoms, together with suppressed RORA expression in PBMC and increased secretion of proinflammatory cytokines, including IL1β, IL6, MCP1 and IL17A." (PMID 35164690, 2022). "We found that maternal diabetes-mediated autism-like offspring had RORA suppression in IEC with significant GI symptoms, including oxidative stress and inflammation in IEC, increased intestine permeability and altered microbiota compositions." (PMID 35164690, 2022). "It is noteworthy that RORA is expressed in numerous brain tissues (e.g. the cerebellum, pineal gland and hippocampus) and it was demonstrated to be correlated with autism and cerebral ataxia." (PMID 35934844, 2022). "The in vivo mouse study showed that prenatal RORA deficiency mimicked maternal diabetes-mediated autism-like behavior (ALB); postnatal expression of RORA in amygdala ameliorated, while postnatal knockdown of RORA mimicked, maternal diabetes-mediated ALB." (PMID 35027651, 2022). "Our in vitro study showed that transient hyperglycemia induces persistent RORA suppression in human neural progenitor cells, and the in vivo mouse study showed that maternal diabetes induces RORA suppression in neurons in autism-like offspring." (PMID 35027651, 2022). "Our results showed that RORA expression was significantly suppressed in brain tissues of maternal diabetes-mediated autism-like mouse models." (PMID 35164690, 2022). "Maternal diabetes-mediated autism-like mouse offspring display RORA suppression in the brain, PBMC and IEC with oxidative stress and inflammation." (PMID 35164690, 2022). "In this study, we aim to investigate the contribution of RORA to GI symptoms through a maternal diabetes-mediated autism-like mouse model." (PMID 35164690, 2022). "In this study, we aim to investigate the potential effect and mechanisms of RORA suppression on autism-like behavior (ALB) through maternal diabetes-mediated mouse model." (PMID 35027651, 2022).